IL21 (interleukin 21)
Diseases named in the same sentence as IL21 in open-access papers (continued):
Sharing a sentence is not in itself a finding about the gene and the disease.
psoriasis (70 papers, 2010 to 2025). An autoimmune condition characterized by red, well-delineated plaques with silvery scales that are usually on the extensor surfaces and scalp. "AD is classically associated with dysregulation of the Th2 subset (IL-4, IL-5, IL-13, and IL-31), whereas the Th17 subset (IL-17, IL-21, and IL-22) has been implicated in the pathogenesis of psoriasis." (PMID 40535962, 2025). "IL-23 stimulates Th17 cells to produce IL-17 and IL-21, driving neutrophil infiltration and promoting the inflammatory response associated with psoriasis." (PMID 39684717, 2024). "IL-17 receptors, RUNX1, and IL-21 with miR-215-binding UTRs constitute Th17 subset-specific signature molecules, implying the potential role of miR-215 in psoriasis-associated Th17 dysregulation." (PMID 37700769, 2023). "The genomic region (4q27) including the IL21 gene is associated with psoriasis and SNPs in this locus are associated with higher IL‐21 levels in other inflammatory disorders." (PMID 35677926, 2022). "IL-21 levels in the skin are associated to psoriasis severity, and this cytokine acts on keratinocytes by inducing proliferation and epidermal hyperplasia signalling via STAT3." (PMID 29316631, 2018). "In mouse models of psoriasis elevated levels of IL-21 are associated with CK6 and CK16 overexpression, consistent with an abnormal keratinocyte proliferation." (PMID 26351408, 2015). "Studies have identified IL-21 as a key factor in psoriasis pathology, with elevated levels associated with the severity of psoriasis, promoting an inflammatory environment by encouraging Th17 differentiation while inhibiting Treg cells, which typically act to moderate immune responses​." (PMID 40161116, 2025). "However, the mechanism by which IL-21 affects the pathogenic progress of psoriasis remains poorly understood." (PMID 31440249, 2019). "Furthermore, a previous study identified that three SNPs from chromosome 4q27, containing genes for IL-2 and IL-21, were involved in the genetic susceptibility to psoriasis and psoriatic arthritis." (PMID 24944624, 2014). "Interleukin-21 is a cytokine that plays a critical role in the differentiation and function of Th17 cells, which are central to the pathogenesis of psoriasis." (PMID 40161116, 2025). "By focusing on IL-21, research can aim to disrupt the chronic inflammatory loop characteristic of psoriasis, restore immune equilibrium, and reduce the disease’s burden on patients’ lives​." (PMID 40161116, 2025). "They found increased IL-21 and IL-21 receptor (IL-21R) expression in lesional skin and peripheral blood samples of psoriasis patients​." (PMID 40161116, 2025). "Future studies can prioritize understanding IL-21’s specific signaling mechanisms in psoriasis, enabling precise therapeutic interventions that maximize efficacy and minimize adverse effects." (PMID 40161116, 2025). "Interleukin-21 has been shown to contribute to psoriasis pathogenesis via the proliferation of CD4+ T cells, increasing function and differentiation of Th17 cells, and downregulation of regulatory T cell (Treg) cell differentiation." (PMID 40161116, 2025). "In recent years, exploring novel treatment avenues such as targeting IL-21, small nucleolar RNA (snoRNA) Snora73, the gut microbiome, and natural remedies have shown increasing promise in managing psoriasis." (PMID 40161116, 2025). "Since Th1, Th17, and Thf cells can all produce IL-21, which plays a role in psoriasis, we analyzed IL-21 in our proliferation assays." (PMID 40270954, 2025). "In conclusion, IL-21 is a promising target for novel psoriasis therapies, given its central role in modulating the balance between pro-inflammatory and regulatory T-cell populations​." (PMID 40161116, 2025). "Interleukin-21 has recently gained attention as a potential therapeutic target in psoriasis due to its role in promoting inflammatory immune responses, mainly through modulation of T helper cell subtypes, such as Th17 and Tregs." (PMID 40161116, 2025).
psoriasis (continued). "In general, proinflammatory cytokines and factors stimulating proliferation in psoriasis are produced mainly by T cells (IL-17, IL-21, IL-22, IFN-γ), DCs (TNF-α, IL-6, IL-20, IL-23, NO), and KCs (antimicrobial peptides (AMPs), IL-20, chemokines)." (PMID 38642273, 2024). "IL-23 and IL-17A are pivotal inflammatory factors in the pathogenesis of psoriasis, with IL-23 promoting the secretion of IL-17 and IL-21 by Th17 cells, enhancing neutrophil infiltration and inducing inflammation in psoriasis." (PMID 38239345, 2023). "IL-21, a T cell-derived cytokine, leads to epidermal hyperplasia in psoriasis by inducing keratinocyte proliferation." (PMID 37700769, 2023). "STAT3 conveys signals from psoriatic cytokines, such as IL-6, IL-17, IL-21, IL-22, and IL-23, to the nucleus and triggers an inflammatory response, which is involved in the pathogenesis of psoriasis." (PMID 35116069, 2022). "One of the sources of IL-17A in psoriasis is Th17 cells, then they are stimulated to secrete further cytokines by IL-23, which include (besides IL-17A): IL-17F, IL-21, IL-22, IL-26, and TNF-α." (PMID 36226313, 2022). "On the other hand, biological agents targeting TNF, IL-23 and IL-17 have shown promising efficacy during the clinical treatment of psoriasis, while IL-6 inhibitors, IL-21 inhibitors and recombinant human IL-10 treatment didn’t attain the results as expected." (PMID 34975883, 2021). "JAK inhibitors suppress the JAK/STAT signaling pathways and, thus, block the effects of inflammatory cytokines, such as IL-6, IFN-γ, IL-22, and IL-21, which are involved in the pathogenesis of psoriasis." (PMID 34501328, 2021). "And Tfh cells, which has been proved to be one of the major sources of IL-21, are also involve in the pathogenesis of psoriasis." (PMID 34975883, 2021). "IL-21 is highly expressed in skin lesions and peripheral blood of psoriasis patients, which is required for epidermal hyperplasia and Th17-cell polarization." (PMID 32684837, 2020). "To verify the role of IL-21 in the progression of psoriasis, we administrated the anti-IL-21R antibody to neutralize the IL-21 signaling pathway through IMQ-induced psoriasis-like BALB/c mouse models." (PMID 32684837, 2020). "We also found that the expression of Foxp3, which is essential for the differentiation and function of Treg cells, was reduced after the treatment with IL-21, both in psoriasis patients and healthy individuals." (PMID 31440249, 2019). "This study shows the possibility of using psoriasin, nestin, Krt16, and IL-21 as biochemical markers of psoriasis and highlights the correlation of these with biomarkers of obesity (BMI, leptin, and resistin)." (PMID 31275060, 2019). "Our results showed that more CD4+ T cells were proliferated after being stimulated with IL-21, both in psoriasis patients and healthy individuals." (PMID 31440249, 2019). "As psoriasis is a systemic disease, we tested the level of IL-21 in the peripheral blood of psoriasis patients and healthy individuals." (PMID 31440249, 2019). "Consistent with the previous studies, we found that the mRNA level of IL-21 and its receptor was higher in the lesional skin of psoriasis patients compared with the skin of healthy individuals." (PMID 31440249, 2019). "The objective was to establish if psoriasin, nestin, Krt16, and IL-21 were possible biomarkers of psoriasis and to correlate them with Body Mass Index (BMI), leptin, and resistin (biomarkers of obesity)." (PMID 31275060, 2019). "Our results showed that IL-21R is highly expressed in PBMCs and in the lesional skin of psoriasis patients, and that IL-21 can promote CD4+ T cell proliferation and Th17 cell differentiation and also the secretion of IL-17A and IL-22." (PMID 31440249, 2019). "Nevertheless, in the human psoriasis xenograft mouse model, the blockade of IL-21 alleviates skin inflammation, suggesting the critical role of IL-21 in human psoriasis." (PMID 31440249, 2019).
psoriasis (continued). "Our result revealed that an increased number of CD4+ T cells secrete IL-21 and express IL-21R in the PBMCs derived from psoriasis patients." (PMID 31440249, 2019). "The results of western blotting and immunohistochemical staining confirmed the higher expression of IL-21 and IL-21R in the protein level of psoriasis patients compared with the healthy individuals." (PMID 31440249, 2019). "In the current study, IL-21 was significantly increased in both the lesional skin and peripheral blood of psoriasis patients consistent with the previous studies, suggesting the significant role of IL-21 in the pathogenesis of psoriasis." (PMID 31440249, 2019). "As IL-21 was mainly expressed in CD4+ T cells in the lesional skin of psoriasis patients, we then investigated the IL-21 expression in CD4+ T cells in PBMCs." (PMID 31440249, 2019). "Genome-wide association studies have identified risk variants in the Il21 gene for SLE, psoriasis, and psoriatic arthritis." (PMID 30013031, 2018). "Serum levels of IL-21 are higher in patients with psoriasis than in controls and positively correlate with PASI score." (PMID 30065726, 2018). "An IL21 blocking antibody has been shown to reduce epidermal thickness and inflammation in a human psoriasis xenograft SCID model." (PMID 28199695, 2017). "The association at IL21 is substantiated biologically by previous work demonstrating upregulation of IL21 and its receptor IL21R in skin lesions from psoriasis and atopic dermatitis (AD) patients." (PMID 28199695, 2017). "Th17 cells and the cytokines secreted by them, such as IL-17A, IL-17 F, IL-22 and IL-21, play a role in numerous chronic inflammatory diseases including psoriasis." (PMID 27581210, 2016). "Some studies have shown increased serum levels of IL-21 in psoriasis patients with respect to healthy controls." (PMID 26351408, 2015). "In a HapMap-CEU population, a large block (480 kb) of linkage disequilibrium encompassing KIAA1109/Tenr/IL2/IL21 showed genetic associations with type 1 diabetes mellitus (T1DM), RA, juvenile idiopathic arthritis (JIA), psoriasis and psoriatic arthritis(PA)." (PMID 23889847, 2013). "In a human psoriasis xenograft mouse model the blockade of IL-21 activity by anti-IL-21 antibodies resolves IL-21-induced inflammation and reduces keratinocyte proliferation." (PMID 23531535, 2013). "Within human skin, IL-21 promotes keratinocyte proliferation and is thought to be involved in the epidermal hyperplasia of psoriasis." (PMID 23226194, 2012). "Because IL-17, IL-22 and IL-21 have been largely implied in skin homeostasis as well as inflammatory skin disorders such as psoriasis and atopic dermatitis, it is of importance to know which skin DC can induce the cytokine-producing T cells." (PMID 23226194, 2012). "Recently, genome-wide association studies have provided convincing evidence that the chromosomal 4g 27 region that harbors the IL-21 and IL-21 genes is associated with chronic inflammatory disorders, including SLE, inflammatory bowel disease and psoriasis." (PMID 22030011, 2011). "Thus, IL-21 inhibitors show potential as a therapeutic option due to their ability to interfere with the immunological pathway of psoriasis." (PMID 40161116, 2025). "Notably, TFH cells in psoriasis are activated and have upregulated IL-21, IL-17, and IFN-γ production." (PMID 38642273, 2024). "Importantly, these include IL‐6, IL‐21, and TGFb1 cytokines that have been shown to contribute to Th17 differentiation, a T cell subtype that marks psoriasis." (PMID 36855912, 2023). "This happens for IL-6, IFN-γ, IL-22, and IL-21, all involved in psoriasis." (PMID 36901778, 2023). "Similarly, IL‐21 can drive TH17 differentiation in psoriasis, with higher levels of IL‐21 reported in lesional skin of psoriatic patients." (PMID 35677926, 2022).
psoriasis (continued). "Inhibition of IL-17 mediated amplification of psoriasis inflammatory loop may translate in lower levels of IL-21 and IL-23, affecting the skewing of Th17 populations towards Th1-like cell subsets." (PMID 35925616, 2022). "Th17 cells produce cytokines such as IL-21, IL-17, and IL-22 to accelerate psoriasis symptoms." (PMID 35409158, 2022). "For example, upregulated IL-21 cytokine has been noted in psoriasis, which has been speculated to be involved in IgE production in psoriasis." (PMID 36314037, 2022). "The same strategy of halting the elevated pro-inflammatory cytokine in psoriasis may work with IL-21, which is majorly secreted by CD4+ T cells, Th17 cells and T follicular helper cells." (PMID 35203707, 2022). "In a study of patients with psoriasis, it is found that IL-21 up-regulates RORγt expression and down-regulates the expression of Foxp3, increases secretion of IL-17A and IL-22, and finally induces T-helper 17 (Th17) and Tregs imbalance and promotes inflammation in psoriasis." (PMID 34490267, 2021). "Cytokines or mediators that are upregulated in psoriasis, such as IL-23, IL-17A, IL-6, and IL-21, may induce the conversion of Tregs into Th17/Th1 cells." (PMID 34501328, 2021). "Moreover, psoriasis has been associated with increased inflammatory cytokines, in which the IL-23/Th17 axis with TNF-α, IL-21, and IL-22 play a role in the control of inflammation." (PMID 34722590, 2021). "Moreover, neutralizing IL-21R with anti-mouse IL-21R antibody significantly reduces IMQ-mediated accumulation of MDSCs in skin lesions and splenic Th17 cells, indicating targeting IL-21 is a therapeutic approach for psoriasis." (PMID 32684837, 2020). "Hence, IL-21 plays a significant role in the imbalance of Th17 and Treg cells in psoriasis patients." (PMID 31440249, 2019). "Thus, in the present study, we investigated the effects of IL-21 on CD4+ T cells of psoriasis patients." (PMID 31440249, 2019). "Herein, the balance of Th17 and Treg cells is impaired in psoriasis patients, and this may be due to the upregulated expression of IL-21 in moderate-to-severe plaque psoriasis patients." (PMID 31440249, 2019). "IL-21 is a Th17-related cytokine and plays an important role in the pathogenesis of psoriasis." (PMID 31440249, 2019). "Moreover, IL-6, IL-21, IL-22, IL-26, and IL-29, which participate to the amplification and maintenance of the inflammatory loop in psoriasis, all signal via STAT3." (PMID 29316631, 2018). "In addition to IL-21, snoRNA Snora73 has emerged as a novel target for psoriasis treatment." (PMID 40161116, 2025). "Targeting IL-21, Snora73, and the gut microbiome, as well as utilizing natural treatments, may provide new opportunities for more effective, personalized management of psoriasis." (PMID 40161116, 2025). "However, the dominant immune response in psoriasis is T helper 17 (Th17), whose characteristic cytokines are interleukin 17A (IL-17A), interleukin 17F (IL-17F), interleukin 21 (IL-21), interleukin 22 (IL-22), interleukin 29 (IL-29), interleukin 8 (CXCL-8), and tumor necrosis factor α (TNF-α)." (PMID 38001807, 2023). "Neutralizing IL-21R by antibody reduces IMQ-induced epidermal thickening through downregulating the infiltration of MDSCs and Th17 cells, suggesting the accumulation of MDSCs exerts important function for the pathogenesis of psoriasis and IL-21 may be a potential therapeutic target in psoriasis." (PMID 32684837, 2020). "Our data revealed that IL-21 could downregulate Foxp3 expression, which is a critical transcription factor in Treg cells, suggesting a role of IL-21 in the impaired function of Treg cells in psoriasis patients." (PMID 31440249, 2019). "First, we investigated whether IL-21 was increased in the psoriasis patients." (PMID 31440249, 2019). "Evidence points to involvement of IFN-γ and IL-21, which activate STAT1 and Th17 cells, but IL-17 is minimally expressed in LP tissues compared to psoriasis." (PMID 40948686, 2025).
psoriasis (continued). "The elevated overall IL-21 secreted by CD4+ T cells and Th17 cells in the serum of psoriasis patients is significantly correlated with a progressive PASI score." (PMID 35203707, 2022). "The cTfh cells were activated in psoriasis with the expression of ICOS, Ki-67, PD-1, and HLA-DR at higher levels and increased production of interleukin (IL)-21, IL-17, and interferon (IFN)-γ." (PMID 34512732, 2021). "Regarding its function in psoriasis, STAT3 activation in psoriatic keratinocytes occurs by IL-17, IL-19, IL-21, IL-22, visfatin, and IL-36." (PMID 34679602, 2021). "In patients with psoriasis, frequency of circulating CD20+ T cells producing IL-17, IL-21, and TNFα correlates with disease activity." (PMID 33628202, 2020). "Overall, consistent with the findings of the lesional skin, IL-21 and its receptor were highly expressed in the CD4+ T cells of PBMCs of psoriasis patients." (PMID 31440249, 2019). "The mRNA levels of IL-21, IL-21R, IL-17A, IL-22, IL-23, RORγt, and IFN-γ were increased, whereas the mRNA level of Foxp3 was decreased in the PBMCs of psoriasis patients." (PMID 31440249, 2019). "cTfh cells are activated in psoriasis, expressing high levels of ICOS, PD-1, HLA-DR, and Ki-67 and secreting increased levels of IL-21, IL-17, and IFN-γ." (PMID 27774460, 2016). "Our results showed both increased frequency and activation (indicated by higher expression of ICOS, PD-1, HLA-DR, and Ki-67 and increased production of IL-21, IL-17, and IFN-γ) of cTfh cells in psoriasis patients." (PMID 27774460, 2016). "Despite the fact that IL-21 and IL-33 have been implicated in psoriasis pathogenesis, we could not find any difference in the production of these cytokines between lesional and unaffected skin of psoriasis patients (data not shown)." (PMID 23468834, 2013). "The dysregulation of IL-21 and IL-21R plays a role in multiple immune-mediated diseases, including SLE, psoriasis, RA and other chronic inflammatory diseases." (PMID 23889847, 2013). "This is consistent with existing literature which implicates IL-21 in the pathogenesis of atoimmune diseases such SLE, diabetes and psoriasis." (PMID 21711552, 2011). "In psoriasis patients, peripheral dysfunctional Treg cells demonstrate phosphorylation and the aberrant activation of STAT3 in response to the activities of IL-6, IL-21, and IL-23." (PMID 39684717, 2024). "CD4+ T cells were isolated from the peripheral blood mononuclear cells (PBMCs) from the psoriasis patients and healthy individuals and then treated with or without IL-21 for 3 days." (PMID 31440249, 2019). "Our results showed that the expression of TGF-β was slightly decreased in Treg cells after stimulation with IL-21 in healthy individuals but not in psoriasis patients." (PMID 31440249, 2019). "IL-21 deficient mice showed decreased severity in these diseases models whereas in the imiquimod (IMQ)-induced psoriasis model, inflammation was not alleviated in the IL-21R deficient mice." (PMID 31440249, 2019). "Previous studies have reported the multiple effects of IL-21 on CD4+ T cells in several diseases, so we hypothesized that IL-21 may also have effects on CD4+ T cells in psoriasis patients." (PMID 31440249, 2019). "As the main source of IL-17A in the psoriasis mouse model is γδT cells, not Th17 cells, and IL-21 can inhibit the secretion of IL-17A in γδT cells, no alleviation of inflammation can be observed in IL-21R deficient mice." (PMID 31440249, 2019). "CD4+ T cells were isolated from PBMCs derived from the psoriasis patients and healthy individuals, then treated with or without IL-21 for 3 days." (PMID 31440249, 2019). "Serum levels of IL-1β, IL-4, IL-10, IL-12, IL-17, IL-21, IL-23, visfatin and omentin were not significantly different between psoriasis patients and controls (all P > 0.05)." (PMID 29416693, 2018). "In our study we observed that both IL-21 levels tended to correlate with Psoriasis Area and Severity Index, but no statistical significance was shown (p = 0.0952)." (PMID 26351408, 2015).